ZNF444 (zinc finger protein 444)
Description:
Transcriptional regulator. Binds to the 5'-flanking critical region of the SCARF1 promoter.
Synonyms: EZF-2; EZF2; ZSCAN17; FLJ11137
Tractability: PROTAC: UniProt records ubiquitination sites on it; ubiquitination databases record sites on it.
Gene: Protein-coding gene on chromosome 19 (56,132,599 to 56,160,897, forward strand). Ensembl gene ENSG00000167685.
Subcellular location: Nucleus
Subcellular location (Human Protein Atlas): Nucleoplasm; Nucleoli
Gene Ontology:
Molecular function: sequence-specific double-stranded DNA binding; DNA-binding transcription factor activity, RNA polymerase II-specific; RNA polymerase II cis-regulatory region sequence-specific DNA binding
Biological process: regulation of transcription by RNA polymerase II
Cellular component: nucleolus; nucleoplasm; nucleus
Genetic constraint (gnomAD): Loss-of-function variants: 8 observed, 6.05 expected, observed/expected ratio (o/e) 1.32, 90% interval 0.75 to 1.9. That is too few expected variants to judge how well the gene tolerates losing a copy. Missense variants: 510 observed, 336.03 expected, observed/expected ratio (o/e) 1.52, 90% interval 1.41 to 1.63. Synonymous variants: 258 observed, 163.45 expected, observed/expected ratio (o/e) 1.58, 90% interval 1.42 to 1.75.
Homologues: Orthologues: chimpanzee ZNF444 (99% identical), macaque ZNF444 (96% identical), pig ZNF444 (84% identical), mouse Zfp444 (84% identical), rat Zfp444 (83% identical), dog ZNF444 (82% identical), rabbit ZNF444 (81% identical), Drosophila melanogaster CG12391 (23% identical), Drosophila melanogaster hb (18% identical), zebrafish plagl2 (16% identical), zebrafish ovol1a (16% identical), zebrafish ovol1b (14% identical), and 4 more. Paralogues in human: ZNF202 (37% identical), ZSCAN29 (32% identical), ZNF496 (32% identical), ZNF446 (31% identical), ZSCAN32 (31% identical), ZKSCAN2 (30% identical), ZNF18 (30% identical), ZNF274 (29% identical), ZSCAN18 (28% identical), ZSCAN1 (28% identical), ZNF174 (27% identical), ZSCAN5C (27% identical), and 17 more.
Diseases named in the same sentence as ZNF444 in open-access papers:
ZNF444 is named in the same sentence as 3 diseases in open-access papers, as found by Europe PMC text mining. Sharing a sentence is not in itself a finding about the gene and the disease. The quoted sentences say what the papers report.
bone tumors (1 paper, 2011). "An EWSR1/POU5F1, EWSR1/PBX1 or EWSR1/ZNF444 fusion gene, or a rearrangement of the EWSR1 gene with unknown fusion partner, was detected in close to half of the soft tissue lesions, and in four out of five bone tumors." (PMID 22588017, 2011).
ZNF444 also shares sentences with these, for which no sentence is quoted: Myoepitheliomas (1 paper); tumours (1).